CP (ceruloplasmin)
Diseases named in the same sentence as CP in open-access papers (continued):
Sharing a sentence is not in itself a finding about the gene and the disease.
infection (179 papers, 2004 to 2026). The state of being infected such as from the introduction of a foreign agent such as serum, vaccine, antigenic substance or organism. "In our centre, ciprofloxacin has been used in selected patients who have an infection caused by CP-GNB and who are susceptible to this antimicrobial agent." (PMID 39766528, 2024). "Overall, 296 patients (76.3%) were causing an infection (280 CP-Kp and 16 CP-Ec), and 90 (23.7%) after medical chart review were considered as colonizers (83 CP-Kp and 7 CP-Ec)." (PMID 38703288, 2024). "Infections caused by CP-GNB are typically healthcare-associated and are related to increased costs, length of hospital stay and mortality." (PMID 39766528, 2024). "The objective was to provide detailed information about the clinical and molecular epidemiological features of nosocomial, HCA and CA infections caused by carbapenemase-producing Klebsiella pneumoniae (CP-Kp) and Escherichia coli (CP-Ec)." (PMID 38703288, 2024). "Ceruloplasmin is an acute-phase protein that has been associated with inflammation, severe infection and tissue damage in mammals and fish." (PMID 36088326, 2022). "A549 adenocarcinomic human alveolar basal epithelial cells were inoculated with the wild-type, ppGpp-deficient, and CP strains of A. baumannii at multiplicities of infection of 100 for 2 h." (PMID 34375563, 2021). "Recognizing the urgent need to reduce the dispersion of CP-pathogens, the Hellenic Center for Disease Control and Prevention has drawn up an action plan for the containment of infections caused by multi-drug resistant organisms in health-care facilities." (PMID 32631456, 2020). "Infections caused by CP-CRE are characterized by a higher morbidity and mortality than those caused by carbapenem-sensitive strains." (PMID 30581848, 2018). "In particular, infections caused by CP-CRE are associated with a high treatment failure and consequent high mortality, given the limited therapeutic options and the lack of worldwide availability of new drugs such as ceftazidime/avibactam." (PMID 30581848, 2018). "According to the results of the animal experiments as a whole, including the infection of chickens, ducks and mice, the CP/XH/420/10 virus was more pathogenic than the BP/HuN/414/10 virus." (PMID 27458455, 2016). "Conversely, TNF-α was associated significantly with groups having active infection (CP Ag+ and INF) indicating a possible association with filarial infection rather than pathology alone." (PMID 22685406, 2012). "Co-IP MS, RNA-seq, LCA, BiFC, and FRAP indicated that the discrepancy in the liquid-liquid phase separation (LLPS) between PMMoV CP and PMMoV CPY13A with I3QHX5 might be the main cause of infection differences." (PMID 40460937, 2025). "However, the European Society of Clinical Microbiology and Infectious Diseases (ESCMID) guidelines do not mention the possibility of using fluoroquinolones for treating infections caused by CP-GNB." (PMID 39766528, 2024). "A total of 88 cases of CP-CRE healthcare-associated infections were diagnosed in the study period." (PMID 35884196, 2022). "It has been found that the infections caused by carbapenemase-producing carbapenem-resistant Enterobacteriaceae (CP-CRE) are associated with greater threat to human health with high fatality rates and increased healthcare cost, compared to the infections caused by non-CP-CRE." (PMID 33434203, 2021). "Asymptomatic colonization with CP-CRE can cause clinical infection." (PMID 34063374, 2021). "In addition, distinguishing carbapenemase producers from non-carbapenemase producers is important to prioritize newer antibiotics for the infection caused by CP-CRE, which might delay the development of resistance to novel drugs." (PMID 33434203, 2021). "Nevertheless, it is evident that copper is an acute-phase reactant; therefore, it has been reported that its serum levels increase in response to infection and inflammation due to elevated levels of the circulating copper protein, ceruloplasmin." (PMID 39997063, 2025).
infection (continued). "In the human infection of Candida albicans, serum ceruloplasmin is used as a copper source by the microbial pathogen during copper starvation." (PMID 39560500, 2025). "Since CP sequesters Mn during infection, we assessed SOD activity in GAS grown in the presence of CP." (PMID 38869295, 2024). "During the early stage of infection at 1 dpi, the EM/CP-infected group exhibited substantial numbers of natural IEL subpopulations, including TCRαβ+CD4-CD8-, TCRαβ+CD8αα+, TCRγδ+, and TCRneg cells in the jejunum compared to the control and EM groups." (PMID 38455042, 2024). "Of the three resistant microbes, CP-GNB was most reported with a foreign country as the place of infection (12/24, 50%)." (PMID 37980302, 2024). "In our various murine models, we assessed the ability of Cp 090104 and CP-derived BLPs to modulate adaptive humoral and cellular immune responses against S. pneumoniae, both post-infection and post-nasal immunization, with two pneumococcal vaccines." (PMID 38675794, 2024). "The host deploys nutritional immune factors, such as calprotectin (CP), to infection sites to withhold metals and inhibit microbial growth (4, –, 8)." (PMID 38869295, 2024). "In the partial correlation analysis, with post-COVID CONUT scores, age, sex, and HD duration as covariates, the pre-infection CONUT score showed a significant association with MDAs (r = 0.65, p < 0.0001) and ceruloplasmin levels (r = −0.27, p = 0.004)." (PMID 38804402, 2024). "Increased mRNA level of OLFM4 during peak infection, particularly in EM + CP treatment, is likely related to the promotion of intestinal epithelial cell regeneration in response to the increased intestinal inflammation." (PMID 39759108, 2024). "Overall, 386 patients were included (363 [94%] with CP-Kp and 23 [6%] CP-Ec); in 296 patients (76.3%), the CPE was causing an infection." (PMID 38703288, 2024). "The study also demonstrated that the increase in ceruloplasmin levels corresponded with the severity of the infection." (PMID 39574108, 2024). "Carbapenemase-producing Enterobacterales (CP-CRE) are recognized as a clinical challenge since therapeutic options are limited and infections with such organisms are associated with significant mortality." (PMID 36786132, 2023). "Carbapenemase-producing, carbapenem-resistant P. aeruginosa (CP-CRPA) is a notable threat globally and infections caused by CP-CRPA are associated with high morbidity and mortality." (PMID 36786132, 2023). "The current working model for CP in extracellular metal sequestration begins with neutrophil recruitment to an infection site." (PMID 36826733, 2023). "Because CP sequesters multiple M(II), the “relevant” metal-sequestering activity(ies) will depend on metal availability at a given infection site as well as the nutritional requirements of the pathogen(s)." (PMID 36826733, 2023). "We examined the impacts of HSP70 overexpression and knockdown on BVDV virus replication at various time points following BVDV (CP/NCP) infection." (PMID 37374975, 2023). "After 7 dpi, we detected WYMV infection by the accumulation of WYMV CP, measured by qRT‐PCR in these inoculated seedlings." (PMID 36715229, 2023). "While it mainly functions as an amplification pathway of the CP and LP, shortly after an infection, the AP can also act as a first line of defence against invading pathogens, before an antibody response is mounted." (PMID 37105991, 2023). "CPE infections, especially carbapenemase-producing K. pneumoniae (CP-Kpn), are one of the most significant threats to public health because the carbapenems are among the last available therapeutic drugs for eradicating these infections." (PMID 36671308, 2023). "This process is downregulated a few hours after the infection with NCP-BVDV biotype while continuing unrestrictedly in the case of CP-BVDV biotype infection." (PMID 37483297, 2023).
infection (continued). "In group 2 (rabbits with autologous surgery and anti-TB treatment), two months after infection, there was a statistically significant decrease in CP levels compared both with initial values and with values registered 18 days after infection." (PMID 37626725, 2023). "The same analytic method revealed ascites (p = 0.000), CP score (p = 0.001), infection during treatment (p < 0.001), and ATP-binding cassette subfamily G member 2 (ABCG2)-rs2231142 genotype (p = 0.003) as independent predictors in cohort-2 patients." (PMID 35566676, 2022). "Elevation of Cu levels within infection sites is attributed predominately to the infiltration of the ferroxidase ceruloplasmin (CP) during the acute-phase response." (PMID 36413018, 2022). "Over time, though, the infection progressed, MG gradually destroyed the immune defences of CP-II cells." (PMID 36471418, 2022). "Next, we carried out analyses of patients who contributed more than one CP-Kpn isolate to distinguish within-host evolution or mixed infection of clustering." (PMID 35546482, 2022). "Usually, the expression of the heterologous gene is controlled by an additional copy of PVX SGP so that a fourth sgRNA, consisting of the heterologous gene and CP, is produced during infection." (PMID 35632840, 2022). "Our results suggest an initial increase in plasma ceruloplasmin levels in M/L fish followed by a later decrease during the course of infection in the H group." (PMID 36088326, 2022). "Noncarbapenemase-producing carbapenem-resistant Enterobacterales (non-CP-CRE) are increasingly recognized as important contributors to prevalent carbapenem-resistant Enterobacterales (CRE) infections." (PMID 36036505, 2022). "CP is abundantly present at sites of infection and is mainly produced by myeloid cells, especially neutrophils where it makes up about 50% of the cytoplasmic protein content." (PMID 35893559, 2022). "In terms of the infection site, the majority CP-CRE isolates were derived from blood (34.1%), urine (34.1%), and surgical wounds (20.5%)." (PMID 35884196, 2022). "In conclusion, K. pneumoniae BSIs remained stable during the last five years, with a high rate of infections due to CP-Kp." (PMID 36290072, 2022). "Fourteen proteins, including three apolipoproteins, two globins, complement component 3 (C3), ceruloplasmin and biotinidase, were negatively correlated with the infection intensity." (PMID 36088326, 2022). "Infected birds responded similarly to uninfected birds to the dilution of the CP content of their diet during all stages of the infection." (PMID 34794080, 2022). "Univariate analysis showed that K. pneumoniae, high-level carbapenem resistance, CP-CRE and KPC-CRE were infection risk factors after CRE colonization." (PMID 34215214, 2021). "In this case, the enhanced T cell activation in response to ΔtcpAh mutant infection can be impaired by the restoration of CP-TcpAh." (PMID 34305858, 2021). "The positive linear correlation of serum Cu and Se observed is peculiar, as Se and SELENOP decline in infection, whereas Cu and CP increase." (PMID 34072977, 2021). "In the infection group, 87.9% of strains were CP-CRE and KPC (72.4%) was the most common carbapenemase type." (PMID 34215214, 2021). "The expression of the CP gene of SCMV increased with the infection progression, indicating the replication of the SCMV genome and successful infection of SCMV." (PMID 33809985, 2021). "Since one molecule of ceruloplasmin binds six atoms of copper, even a modest increase in ceruloplasmin during infection can account for a substantial elevation in serum copper." (PMID 34069220, 2021). "In the first experiment, ceruloplasmin activity increased significantly in all groups, except for the control group, 24 h after infection." (PMID 34359116, 2021). "In roots, at early time-points (1 and 2 dai) upon infection of line CP888 with F. verticillioides (CP+FV), the expression level of PAL remained unchanged when compared to the mock control CP888 plants (CPC)." (PMID 34575762, 2021).
infection (continued). "Ceruloplasmin is a positive acute-phase protein that is key for maintenance of iron homeostasis, and its production increases during periods of infection and inflammation, making it a good marker of inflammation in transition dairy cows." (PMID 33795002, 2021). "CP-CRE colonization can be a precursor to infection, more so in an immunocompromised population such as neonates." (PMID 34063374, 2021). "Ceruloplasmin is an acute phase protein induced in response to inflammation, trauma, or infection, and its levels are also induced during infection." (PMID 34069220, 2021). "During infection of antigens, PA28αβ as well as the β1i, β2i, and β5i subunits of the CP would be induced by IFN-γ to form immunoproteasomes, facilitating the generation of MHC class I ligands for subsequent antigen presentation." (PMID 33531497, 2021). "In the non-infection group, approximately 64.6% of strains were CP-CRE, among which NDM (42.2%) was the most abundant, followed by KPC (16.8%)." (PMID 34215214, 2021). "Infection with ESBL- and CP-Kp is associated with staggeringly high mortality (>50%) and excessive healthcare costs, leading the Centers for Disease Control and Prevention to categorize ESBL- and CP-Kp as serious and urgent threats, respectively." (PMID 33930099, 2021). "Serum amyloid A (SAA), haptoglobin (HP), and ceruloplasmin (CP) were produced by liver and considered prognostic biomarkers for acute inflammation in dogs as a result of tissue infection or inflammation." (PMID 33363329, 2020). "The genetic signature in the parasite changes strongly with changing cost of infection (s), irrespectively of cH and cP." (PMID 32203545, 2020). "The expression of the PRSV CP gene in tobacco offered protection against infection by a broad spectrum of potyviruses such as TEV, PVY, and pepper mottle virus (PeMV)." (PMID 32708998, 2020). "Infection and colonization rates by CP-Kp strains in Greek tertiary care hospitals are considered amongst the highest in Europe." (PMID 32631456, 2020). "At 48 hours after infection, RT‐qPCR result showed that gga‐miR‐451 level was significantly increased in the CP‐II cells." (PMID 32307881, 2020). "Infection of PMMoV in the symptomatic plants was confirmed by reverse transcription-polymerase chain reaction (RT-PCR) using PMMoV CP gene specific primers." (PMID 33121441, 2020). "Transgenic potato Bt6 expressing PVY CP gene provided resistance to primary and secondary infections by PVY when transmitted by aphids." (PMID 32708998, 2020). "We interpret that poor CP stability in a PVAAG infection is indicative of its degradation due to reduced incorporation into particles or instability of the assembled particles." (PMID 33031436, 2020). "CP is an acute phase reactant that increases in concentration in serum/plasma during infection and inflammation." (PMID 30774579, 2019). "CP is also an acute phase protein induced in response to inflammation, trauma, or infection with bacteria, viruses and protozoans." (PMID 30774579, 2019). "To further test the versatility of our dsRNA reporter transgenic N. benthamiana lines, we next followed progress of the recombinant PVX.mCherry-CP infection over a 17 h time period." (PMID 29449856, 2018). "CP-CRE colonisation has been shown to correlate positively with the incidence of infection attributed to CP-CRE organisms, particularly in an intensive care unit (ICU) setting." (PMID 30111322, 2018). "A total of 128 patients were included in the study: 55/128 (43%) with infections due to CP-CRE and 73/128 (57%) with infections due to CSE." (PMID 30581848, 2018). "Lastly, successful infection of the developing grains by BSMV:GFP or BSMV:PDSas was confirmed by positive detection of viral CP transcripts." (PMID 28983311, 2017). "All of the flexible membrane groups had significantly lower infection efficiencies than the CP group." (PMID 28595633, 2017).
infection (continued). "In particular, proteins participating in iron sequestration were up-regulated during infection, including ferritin, ceruloplasmin, lactoferrin, and haptoglobin." (PMID 27982111, 2016). "In considering the extracellular functions and fate of CP, we questioned how CP copes with the harsh environments that it encounters at sites of infection, inflammation, and in the intestinal lumen." (PMID 26925211, 2016). "Collectively, it suggest that CP is strong enough to inhibit the viral replication and promoted the survival of mice against lethal infections of diverse influenza A viruses." (PMID 27484768, 2016). "The silent and severe infection groups had significantly higher B cell counts at the CP than at baseline (p < 0.05)." (PMID 24646014, 2014). "What's more, in the total 72 cases of aGvHD in systemic monitoring as well as symptomatic follow-up, infection+ and infection- patients had similar ceruloplasmin level at diagnosis of different grades of aGvHD." (PMID 23505556, 2013). "A significant (CP-by-infection) interaction effect meant that the geometric mean (GM) for the marker in the CP Ag+ group is significantly different from GM expected from the combined effects of CP and infection." (PMID 22685406, 2012). "The relationships among the Type-2 cytokines and MMP/TIMP ratios were assessed in those subjects with active infection (CP Ag+ and INF)." (PMID 22679524, 2012). "We tested for three effects (CP effect, infection effect, and CP-by-infection interaction effect) on each of 12 markers using linear models on the log transformed responses." (PMID 22685406, 2012). "PHYVV and PepGMV CP mutants, when inoculated as a single infection, usually produced mild symptoms in the inoculated leaves, and rarely in systemic tissues." (PMID 21385390, 2011). "Because these viruses induced TCD8+ responses to different degree depending on the route of infection, it was concluded that CP and DP contribute differentially to the anti-VACV TCD8+ response." (PMID 20169189, 2010). "Determining resistance mechanisms could lead to better infection control measures, such as patient isolation to prevent CP-CRE spread in hospitals." (PMID 41036946, 2025). "Nevertheless, data on oral therapy for CP-GNB infections are scarce." (PMID 39766528, 2024). "This was consistent with the known role of ceruloplasmin as an acute phase reactant, whose levels may rise in response to inflammation and infection." (PMID 39574108, 2024). "CP has increased expression during inflammation and infection." (PMID 38890712, 2024). "The level of CP was lower than on day 18 after infection and lower than in group 1 (IC)." (PMID 37626725, 2023). "Notably, ceruloplasmin has been shown to deliver Cu to immune cells, thereby supporting immune responses after infection and immunization, and likely affecting the balance of Cu-free apoenzyme to Cu-loaded ceruloplasmin." (PMID 37886755, 2023). "Two months after infection in groups 2 (with autografting) and 3 (with composite scaffold surgery), the decrease in ceruloplasmin levels and an increase in the activity of purine metabolism enzymes (total ADA and ADA-1), regulating the level of adenosine, were detected." (PMID 37626725, 2023). "However, this study was necessary due to the observation of a rising trend of infections due to CP-CRE in Cuba, and it is the first study to address this issue for perioperative patients in this region." (PMID 35884196, 2022). "During CymMV infection or overexpression of CymMV_CP or CymMV_TGBp1, pPaAGO5b_941 exhibited maximal activity, followed by pPaAGO5b_full-length, pPaAGO5b_1782, pPaAGO5b_1582 as compared to those without CymMV infection or the expression of CymMV_CP or CymMV_TGBp1." (PMID 36077222, 2022).